BRCA1 (BRCA1 DNA repair associated)
Diseases named in the same sentence as BRCA1 in open-access papers (continued):
Sharing a sentence is not in itself a finding about the gene and the disease.
tumor (continued). "Another tumor morphology pattern of BRCA1 carriers comprise of pushing margins which avoid of tubular formation, trabecular, syncytial and circumscribed growth pattern and necrosis." (PMID 24312913, 2013). "BRCA1 is considered to be a differential modulator of tumor response to cisplatin and taxanes, and BRCA1 levels are reportedly associated with chemosensitivity to cisplatin and taxanes." (PMID 23496813, 2013). "We have found positive BRCA1 protein nuclear staining in frozen and FFPE tumor and lactating tissue from a patient with a BRCA2 mutation." (PMID 23855721, 2013). "BRCA1 mRNA expressions were detected successfully in total 144 tumor samples by using quantitative real-time PCR and the median mRNA expression levels of BRCA1 relative to reference gene of β-actin were 11.96 (range 0.39–70.03)." (PMID 23326344, 2013). "The molecular analysis revealed the loss of the wild-type BRCA1 allele in both the epithelial and the mesenchymal components of the tumor, supporting the role of BRCA1 in its development." (PMID 23374397, 2013). "A previous study demonstrated that males had higher tumor expression levels of BRCA1 compared to females (P=0.020)." (PMID 24649266, 2013). "In a second study, it was found that BRCA1 knockdown resulted in increased telomerase activity and significant telomere lengthening in tumor cells." (PMID 23802008, 2013). "Mutations/polymorphisms of many cancer susceptibility genes (such as BRCA1, CDKN2A, XPD, VDR, etc.)lead to tumour development." (PMID 23805825, 2013). "Sixteen of eighteen BRCA1 carriers were also in the poor prognosis group together with ER- tumors and tumor with lymphocytic infiltration." (PMID 23599813, 2013). "Our previous studies have shown that BRCA1 protein is localized in tumor cell nuclei and nucleoli in frozen tissue sections, and is co-localized with nucleolin in MCF7 and HeLa cells." (PMID 23855721, 2013). "BRCA1-IRIS overexpressing HME cells form subcutaneous tumors in SCID mice To directly assess BRCA1-IRIS tumor inducing potential, a xenograft mouse model was developed." (PMID 22511931, 2012). "Both BRCA1 and BRCA2 are thought to act as classical tumour suppressor genes and the loss of their cellular functions is thought to occur through bi-allelic inactivation." (PMID 23519070, 2012). "Bach1 enzyme activity as well as the BRCA1-FancJ interaction is essential for DNA repair, checkpoint activation and tumor suppression." (PMID 22369660, 2012). "Located at 17q21, BRCA1 is a tumor suppressor gene that repairs double strand breaks through association with Rad51 protein." (PMID 22852056, 2012). "The BRCA1–Fanconi anemia (FA) pathway is required for both tumor suppression and cell survival, particularly following treatment with DNA damaging agents that induce DNA interstrand crosslinks (ICLs)." (PMID 22792074, 2012). "The BRCA1 tumor suppressor is a 1863 amino acid protein with multiple protein interaction domains that facilitate its roles in regulating DNA repair and maintenance, cell cycle progression, transcription, and cell survival/apoptosis." (PMID 24278741, 2012). "The primary tumor suppressing role of BRCA1 relates to the maintenance of genomic integrity through regulation of DNA replication, repair, and transcription, in addition to various cell cycle checkpoints that ensure survival of healthy cells." (PMID 24278741, 2012). "Olaparib (AZD2281) is a potent oral PARP inhibitor that has exhibited monotherapy activity in tumour cells with defective components of homologous recombination, including cells with the BRCA1−/− and BRCA2−/− genotype." (PMID 22223088, 2012). "Further subgroup analysis, in particular of BRCA1 tumours, was limited by the number of cases available." (PMID 23146383, 2012).
tumor (continued). "BRCA1 is a tumor suppressor that functions in many DNA damage response pathways (i.e., homologous recombination and nonhomologous end-joining during DNA double-strand break repair)." (PMID 22645612, 2012). "Despite extensive knowledge about female BRCA1, BRCA2 and other inherited familial breast tumours at present, little is know of male tumours from high-risk families." (PMID 23146383, 2012). "BRCA1 is a tumor suppressor gene consisting of 5592 base pairs spanning 24 exons; 22 exons of which encode a 220 kDa protein of 1863 amino acids together with two non-coding exons." (PMID 23203101, 2012). "For example, Phase I and II clinical trials have shown that the PARP inhibitor olaparib (AZD2281) can elicit significant and sustained anti-tumour responses, especially in familial cancer patients with BRCA1 or BRCA2 mutant tumours [reviewed in]." (PMID 22933245, 2012). "Earlier studies suggested that the E3 ligase activity of BRCA1 is essential for the DDR and tumor suppression function of BRCA1." (PMID 22369660, 2012). "There is study found that the BRCA1 protein exits in the nucleus of normal mammary epithelial cell and the cytoplasm of tumor cells." (PMID 23276146, 2012). "This is in line with the very recently suggested role of BRCT domain as the main effector of BRCA1 tumor suppressor activity." (PMID 22646717, 2012). "Surprisingly, however, TN/BL/BRCA1-IRIS-positive tumor size was significantly larger than that of HER2+/BRCA1-IRIS-positive tumors (30.6±19.3 vs. 16.1±9.7, p≤0.05)." (PMID 22511931, 2012). "The BRCT domain and its capability to bind phosphorylated protein is required for the tumor suppressor function of BRCA1." (PMID 22369660, 2012). "The pathway analysis revealed that BMP6, BRCA1 and P16 have a role in prevention of neoplasm metastasis." (PMID 22695536, 2012). "PTEN loss has also been shown to decrease expression of Rad51, a DNA repair protein that interacts with the BRCA1 protein in double strand repair, thus enhancing tumor-related genomic instability." (PMID 26097796, 2012). "The large number of mutations occurring in this region, many with loss of large portions of sequence, suggests that this region is important for the tumor suppressor function of BRCA1." (PMID 22737296, 2012). "The BRCT domain of BRCA1 has been indicated important for cell cycle checkpoint, HR and tumor suppression." (PMID 22369660, 2012). "Tumor cell lines with relatively low levels of BRCA1 protein (HCC1937, OVCAR-4) displayed inherent platinum sensitivity, and no significant enhancement of cisplatin was observed with the addition of the HDAC inhibitor." (PMID 21854619, 2011). "Tone provided evidence that the glucocorticoid receptor-mediated anti-inflammatory response post-ovulation is lost in FTE cells deficient in BRCA1 and DAB2 tumour suppressors." (PMID 21699706, 2011). "The major strength of the current study is the large sample of BRCA1 and BRCA2 mutation carriers with SNP and tumour marker information." (PMID 22053997, 2011). "They showed that the BRCA1 promoter was methylated in both PB DNA samples and matched tumor DNA in all examined individuals." (PMID 22129206, 2011). "Tumours with BRCA1 dysfunction, the majority of which are triple negative, namely harbour deficient double-stranded DNA break repair, which leads to increased sensitivity to these agents." (PMID 22933934, 2011). "Case report on 2 related BRCA1 carriers, whose tumor demonstrated pCR upon dose dense AC and sequential weekly paclitaxel." (PMID 21819606, 2011). "BRCA1 has recently been evaluated as a tumour biomarker in a number of malignancies including ovarian, breast and nonsmall cell lung cancer." (PMID 22312502, 2011).
tumor (continued). "Thus, loss of BRCA1 function may impair polarization by altering intracellular cytoskeletal organization, resulting in intermediate filament content consistent with the characteristic basal-like tumor type." (PMID 22110403, 2011). "Two of the discordant tumours tested Sporadic-like in both the MLPA and the aCGH assay, whereas six of the BRCA1-mutation carriers were either classified Sporadic-like by MLPA or aCGH." (PMID 22032731, 2011). "Like many ErbB2-overexpressing tumours, the SK-BR-3 cell line has low levels of BRCA1 protein and mRNA." (PMID 21609478, 2011). "Two of the examined genes, BRCA1 and APC, showed methylation in both tumor and paired PB DNA at frequencies of 4.4% and 4.1%, respectively with one of the paired samples showing methylation of both APC and BRCA1 in tumor and PB DNA." (PMID 22129206, 2011). "S100A8, a calcium-binding protein that complexes with S100A9 and whose expression is suppressed by functional BRCA1, is induced by H-Ras to promote malignant potential (tumor cell invasion and migration)." (PMID 21627793, 2011). "Both normal breast tissue adjacent to the tumours and infiltrating lymphocytes within the tumours that showed strong and uniform staining of BRCA1, were used as internal positive controls." (PMID 23508738, 2011). "The BRCA1 gene is a tumour suppressor that plays an essential role in multiple functions including DNA repair and transcriptional regulation and is regulated by a complex network of DNA binding proteins and coactivators." (PMID 21914189, 2011). "Cell lines and tumours overexpressing ErbB2 have been reported to have particularly low BRCA1 levels." (PMID 21609478, 2011). "Up to now, there are very few literatures on Atm/Brca1 double heterozygosity and their contribution to tumor initiation." (PMID 21849032, 2011). "Thus, BRCA1 dose or mutation type may distinctly affect the tissue architecture and function, leading to differences in the accumulation of stem or progenitor cells, and the resulting tumor type." (PMID 22110403, 2011). "In a previous publication, we reported a significantly better survival in patients with a BRCA1-likeaCGH tumours treated with an intensified alkylating regimen compared to conventional dose chemotherapy." (PMID 22032731, 2011). "If the tumour shows a BRCA1-likeMLPA pattern, in the clinical diagnostics setting, we can continue with extra analysis sorting out the defect (that is, methylation analysis)." (PMID 22032731, 2011). "A significant association was also found between the percentage of CD44+ cells and BRCA1 defective tumours (p<0.001)." (PMID 23508738, 2011). "The odds ratio for high nuclear expression of BRCA1 in tumours with a poor histological grade compared to well-differentiated tumours was 0.24 (95 %CI=0.065-0.933)." (PMID 23508738, 2011). "They proposed that BRCA1-defective xenograft tumor express a high sensitivity to platinum-derived chemotherapy." (PMID 22016618, 2011). "In those studies the authors have examined methylation status of the BRCA1 promoter in PB and paired tumor DNA, however only a subset of the tumors, developed by patients with PB BRCA1 methylation, harbored tumor specific methylation of BRCA1." (PMID 22129206, 2011). "Recently, basaloid human tumors from BRCA1-mutant women provided evidence for a different type of tumor stem cell, derived from a luminal cell-of-origin." (PMID 21541292, 2011). "Given the inverse correlation between BRCA1 and ErbB2 levels in tumours, it was expected that some component of the NRF-1 > GABP > BRCA1 pathway would be sensitive to ErbB2-overexpression." (PMID 21609478, 2011). "Future studies will be focused on the identification of the methylated residues, study of lysine methylation, and determining if there is a correlation between BRCA1 methylation and tumor progression." (PMID 20614009, 2010).
tumor (continued). "In the BRCA1-wild type cells, functional BRCA1, as a tumor suppressor, acts in concert with STAT1 to activate transcription of a subset of IFN-γ gene targets and growth inhibition by cytokine." (PMID 20576130, 2010). "Because of the fundamental and clinical importance of understanding BRCA1 function, we sought to rigorously evaluate the role of this tumor suppressor in response to diverse forms of genotoxic stress." (PMID 21103343, 2010). "HER2 were also assessed by chromogenic in situ hybridization, and BRCA1 mRNA was analyzed in a subset of 41 patients for whom sufficient tumor tissue was available by real-time quantitative PCR." (PMID 20209131, 2010). "In our mouse models, we find that BRCA1 and BRCA2 loss clearly have different impacts on tumor development." (PMID 20735817, 2010). "In the BRCA1 group, median tumor size was 1.8 cm compared to 2.6 for controls (p = 0.003), median MAI was 22 vs 20 in controls (n.s.), and median age was 40 in both cases and controls (n.s.)." (PMID 20398395, 2010). "The identified genes are involved in drug transport and detoxification (ABCB1, DNAJC15, GSTP1, RAB6C), DNA damage repair (BRCA1) as well as tumor cell proliferation/invasion (APC, CDH1, ESR1, HIC, PLAU, RASSF1, SULF2, TGM2)." (PMID 20544021, 2010). "Multifocality (more than one invasive intramammary tumor nodule) was present in 21.8% of sporadic tumors, compared to 25% of BRCA1 related tumors (n.s.)." (PMID 20398395, 2010). "Similar to this case, in MZ twins with mutations in BRCA1 and BRCA2 tumours were detected at the same approximate location and same age." (PMID 20687928, 2010). "A large difference was also seen between tumours from BRCA1 and BRCA2 mutation carriers with tumours from BRCA2 mutation carriers being significantly more methylated than tumours from BRCA1 mutation carriers." (PMID 20565864, 2010). "First, both BRCA1 and BRCA2 are tumour suppressor genes and most often involve wild-type loss of heterozygosity (wt-LOH) in mutation carriers' tumours, resulting in both parental copies of the gene being damaged in line with Knudson's two-hit model." (PMID 20637093, 2010). "Due to this difference in the mouse tumors, there was a BRCA1-specific overlap with human chromosome 1, as all other human tumor groups showed this significantly recurrent gain." (PMID 20735817, 2010). "Together, these differences in tumor profiles suggest that BRCA1 and BRCA2 have different functions in DNA repair pathways, however, we have not been able to identify the nature of this difference using our aCGH profiles." (PMID 20735817, 2010). "The presence of BRCA1-, γH2AX-, or Rad51-foci before treatment or the presence of Rad51-foci after treatment was inversely correlated with tumor response to chemotherapy." (PMID 20205718, 2010). "Surprisingly, that study also showed that let-7 represses several tumour suppressor genes (BRCA1, BRCA2, FANCD2, and PLAGL1, among others) and checkpoint regulators (CHEK1, BUB1, BUB1B, MAD2L1, and CDC23, among others)." (PMID 20179807, 2010). "In its normal state, BRCA1 functions as a tumor suppressor gene, inhibiting the aberrant proliferation of tumor cells." (PMID 20182637, 2010). "In mammalian cells, tumor suppressor BRCA1 uses a Ubc4 homolog as one of its ubiquitin E2 ligases for conjugating ubiquitin to target proteins." (PMID 21103054, 2010). "We found that foci of BRCA1, γH2AX, and Rad51 prior to treatment and EC-induced foci of Rad51 correlated with tumor response when compared either with the mean tumor volume reduction or the tumor response rate." (PMID 20205718, 2010). "Next, we identified syntenic CNAs that co-occurred in both the mouse and human BRCA1-mutated, BRCA2-mutated and control tumor groups." (PMID 20735817, 2010).
tumor (continued). "This approach combines both full pedigree and tumour subtype data to predict BRCA1/2 carrier probabilities." (PMID 20482762, 2010). "In some cases, carrier mutation probabilities for BRCA2 are also altered when information on pathology of the tumour is available, because the BRCA1 and BRCA2 carrier probabilities are interdependent." (PMID 20482762, 2010). "The probability that an individual carries a BRCA1 or BRCA2 mutation given their family history and tumour marker status of family members was computed in sample pedigrees." (PMID 20482762, 2010). "Many genes identified in our study are either known tumor suppressor genes (for example, BRCA1) or previously identified putative tumor suppressor genes (for example, BCR)." (PMID 21108794, 2010). "It is important that normal tissues, in contrast to neoplasms, retain heterozygous BRCA1 status, the presence of a single functional copy of the gene being sufficient for performing its functions." (PMID 22649661, 2010). "This suggests similarities in the mechanisms promoting genomic instability for BRCA1- and BRCA2-associated tumours, possibly relating to deficiency in DNA repair through homologous recombination." (PMID 19589159, 2009). "When stratified by BRCA mutation status, HIF-1α positivity was significantly correlated with BRCA1 (23/32, 72%) compared with BRCA2 (12/32, 38%) and BRCAX (20/49, 41%) associated tumours (P=0.008)." (PMID 19724277, 2009). "BRCA1-related tumours commonly express basal cytokeratins (CK5, CK6, CK14 and CK17), are highly proliferative and show pushing margins." (PMID 19904273, 2009). "In contrast, only eight of 33 (24%) neoplasms with normal or intermediate BRCA1 expression showed reduced BRCA1 expression in the recurrence (p = 0.01)." (PMID 19602291, 2009). "In conclusion, several Brca1 conventional mouse mutants have been generated that show phenotypic variation, ranging from early embryonic lethality to viable mice that develop tumours." (PMID 19904273, 2009). "Together, the human and mouse data suggest that BRCA1 not only functions as a tumour suppressor, but is also required for development of resistance to therapy." (PMID 19904273, 2009). "Increases in BRCA1 protein were significantly more likely than reduction of protein in paired post chemotherapy neoplasms, suggesting a selection for increased BRCA1 expression." (PMID 19602291, 2009). "Brca1 status, in combination with that of other tumor suppressor pathways, influence sensitivity of OSE cells to chemotherapeutic agents." (PMID 20046869, 2009). "In fact, although the majority of BRCA1-mutant tumours lack ER expression, several studies have shown that a small number retain ER positivity." (PMID 19818148, 2009). "Supporting this notion is the finding that sporadic basal-like tumours frequently display a significantly reduced expression of the BRCA1 gene and genomic instability." (PMID 19589159, 2009). "Our observation that restoration of BRCA1 function negates the sensitivity of tumor cells to DZNep would argue against this." (PMID 19709408, 2009). "Tumour genomes within the BRCA1- and BRCA2-related subgroups were characterised by relatively long stretches of genomic alterations, deletions and copy gains along with occasional high-level amplifications." (PMID 19589159, 2009). "This genomic feature was observed in both familial and sporadic tumours displaying a BRCA1- or BRCA2-like spectrum of genomic alterations." (PMID 19589159, 2009). "With the exclusion of the tumours characterized by double positive receptorial status and/or strong HER2 positivity (3+), we identified 22 patients, 10 of whom resulted as BRCA1 mutation carriers." (PMID 19818148, 2009). "Tumours within the simple-profile subgroup appear similar to the BRCA1 and BRCA2 subgroups in terms of altered segment lengths but differ in that they display considerably less complex genomes." (PMID 19589159, 2009).